OR2W6P (olfactory receptor family 2 subfamily W member 6 pseudogene)
Description:
Odorant receptor.
Synonyms: OR2W7P
Gene: Unprocessed pseudogene on chromosome 6 (27,937,465 to 27,938,403, forward strand). Ensembl gene ENSG00000168126.
Subcellular location: Cell membrane
Diseases named in the same sentence as OR2W6P in open-access papers:
OR2W6P is named in the same sentence as 1 disease in open-access papers, as found by Europe PMC text mining. Sharing a sentence is not in itself a finding about the gene and the disease.
OR2W6P shares sentences with these, for which no sentence is quoted: tumor (1 paper).